IL6 (interleukin 6)
Diseases named in the same sentence as IL6 in open-access papers (continued):
Sharing a sentence is not in itself a finding about the gene and the disease.
COVID-19 (continued). "Therefore, in this study, we evaluated whether the circulating levels of TNFR1, TNFR2, and PGRN, in addition to interleukin 6 (IL-6) and CRP, are associated with disease severity and mortality in 80 hospitalized COVID-19 patients." (PMID 36219652, 2022). "Therefore, inhibition of IL-6 could be helpful in COVID-19 treatment, which may be due to its ability to inhibit the cytokine storm." (PMID 35782361, 2022). "Indeed, large studies on the general population showed that patients in severe-stages of COVID-19 had increased amounts of circulating CD14+ CD16+ monocytes which exert inflammatory activity through increased release of IL-6 and interaction with adaptive B and T-cells." (PMID 35267478, 2022). "IMD-0354 did not stimulate IFN-β or IL-6 in macrophages, meaning this drug might not worsen the cytokine storm caused by COVID-19." (PMID 36093376, 2022). "The relationship between lymphocytes subsets with the cytokine interleukin-6 (IL-6) and the characteristics of lymphocyte subsets in single-cell RNA sequencing (scRNA-seq) data obtained from peripheral blood mononuclear cells (PBMCs) were also analysed in COVID-19 patients." (PMID 36403042, 2022). "Interestingly, in this study, the analysis of the differential expression of cytokines in the mild and severe COVID-19 patient groups revealed the expression of IL-2, IL-6, TNF-α, and IFN-γ to be significantly decreased in severe cases as compared to mild cases." (PMID 36584119, 2022). "The presence and ratio of IL-6 and IL-10 may be used as predictors of COVID-19 disease severity." (PMID 35962146, 2022). "We also focused on ethnicity-related differences in cytokines in COVID-19 patients and the results showed that there were lower circulating levels of IL-6 in Asian patients than in European and African patients, suggesting that IL-6 antagonists are recommended to use earlier in western countries." (PMID 35237162, 2022). "Among 50 serum analytes we found that only IL-6 presented a near significant p-value after multiple comparisons testing (p= 0.0583), with an unadjusted p-value of 0.0012 and r = -0.5008 highlighting IL-6 as a likely major driver of hypoferremia during human COVID-19." (PMID 35935705, 2022). "These severe COVID-19 patients show substantially elevated serum levels of proinflammatory cytokines, including interleukin-6 (IL-6) and IL-2, as well as IL-1, IL-8, and tumor necrosis factor, characterized as cytokine storm, which may lead to respiratory failure or even death." (PMID 35308307, 2022). "Moreover, the sex bias seen in the greater severity of COVID-19 symptoms in men may be related to the ability of endogenous E2 in women to reduce IL-6 gene expression." (PMID 35406728, 2022). "Moreover, COVID-19 inflammation activates factor Xa, which is not only the inducer of the extrinsic and intrinsic pathways of coagulation but also stimulates inflammation (through IL-6 induction) and angiogenesis." (PMID 36295042, 2022). "Furthermore, in COVID-19 patients, IL-6 inhibits the immune cell cytotoxicity." (PMID 35893398, 2022). "Following preincubation for 1 h of PBMC with the extract, a significant inhibition of IL-1β, TNF, and IL-6 was observed at a concentration of 5 or 10 μg/mL, with a similar potency when compared to 1 μM dexamethasone, the current reference treatment for COVID-19." (PMID 35455990, 2022). "Moreover, it has been reported that the levels of IL-6 found in the blood of COVID-19 patients are several folds lower than those of patients experiencing a cytokine release syndrome as a consequence of other conditions (e.g., chimeric antigen receptor T cell infusion)." (PMID 35563218, 2022). "Similarly, IL-6/IL-10 ratios can be used to predict the prognosis of multiorgan dysfunction syndrome and mortality after trauma as well as the severity of disease in both pneumonia and COVID-19." (PMID 35261923, 2022).
COVID-19 (continued). "In addition, the abundance of six proteins (IL-6, CKAP4, Gal-9, IL-1ra, LILRB4, PD-L1) increased as the symptoms of patients increased (in the direction: control → mild → severe → critical) and, thus, was associated with COVID-19 severity." (PMID 35269564, 2022). "In addition, some traditional Chinese medicine, such as Glycyrrhizae Radix et Rhizoma (Gancao) and Pinelliae Rhizoma (Banxia), may act by suppressing the IL-6 amplifier and have been used to treat some moderately ill COVID-19 patients." (PMID 36366444, 2022). "Moreover, IL-6 (an inflammatory cytokine), HMGB-1 (a late inflammatory mediator), and KL-6 (reflecting injury and/or remodeling of type II pneumocytes) were associated with outcomes in COVID-19." (PMID 35204430, 2022). "Traditionally, activation of the NLRP3 inflammasone is regarded to be the main inducer of pathogenic pro-inflammatory cytokines IL-1β, IL-18 and IL-6 during COVID-19, but it has become clear that multiple non-conical pathways can contribute and indeed become the dominate inducers of IL-1β." (PMID 35244141, 2022). "Moreover, elevated IL-6 levels correlated with a greater risk of developing severe COVID-19, thus high IL-6 levels were associated with a major hazard for severe COVID-19 in patients with MAFLD than in those without." (PMID 35992140, 2022). "Furthermore, COVID-19 could activate macrophages, resulting in the release of IL-6 with further worsening of the cytokine storm." (PMID 35992140, 2022). "Other pre-existing conditions that have been shown to exacerbate COVID-19 symptoms might have the same origins; for instance, chronic kidney disease is associated with oxidative stress and elevated expression of ACE-2 and cytokines, including IL-6 and CRP." (PMID 35711466, 2022). "Indeed, inflammatory indices, including LDH, CRP and IL-6 may help to identify cases with dismal prognoses in COVID-19 subjects and perform a prompt intervention in order to improve outcomes." (PMID 36619546, 2022). "Recent advances in the pathophysiologic understanding of coronavirus disease 2019 (COVID-19) suggests that cytokine release syndrome (CRS) has an association with the severity of disease, which is characterized by increased tumor necrosis factor α (TNF-α), interleukin (IL)-6, IL-2, IL-7, and IL-10." (PMID 35223745, 2022). "Inhibition of TLR3 by famotidine decreases IL-6 and reduces the risk of intubation and death in patients hospitalized with COVID-19 and alleviates symptoms in non-hospitalized patients with COVID-19." (PMID 35356515, 2022). "However, the role of IL-6 rs1800796 SNP in COVID-19 is controversial." (PMID 36233516, 2022). "Thus, the apparently high IL-6 concentrations used in our basic models are appropriate because they can more faithfully reproduce the biological conditions operating in vivo in patients with COVID-19." (PMID 35665254, 2022). "Also, IL-6 is well known as an important biomarker for COVID-19 patients." (PMID 36254292, 2022). "In addition, at least two different studies have correlated hyponatremia in COVID-19 with elevated IL-6 levels, which could theoretically stimulate anti-diuretic hormone (ADH) release from the pituitary." (PMID 36714113, 2022). "PGE2 may participate in the conversion of pro-inflammatory interleukins (e.g., IL-1β and IL-6) to anti-inflammatory interleukins synthesized by M2 macrophages (e.g., IL-10), which may explain the significant increase in IL-10 in patients who survived COVID-19." (PMID 36233111, 2022). "Importantly, elevated IL-6 level has been tightly associated with ARDS and high mortality of COVID-19 patients; therefore, IL-6 is thought to be a promising therapeutic target to reduce hyper inflammation and prevent the high mortalities of COVID-19." (PMID 34983527, 2022).
COVID-19 (continued). "In addition, ratios of some cytokines and chemokines can be used, such as IL-6/IFN-γ ratio, which was demonstrated in a meta-analysis to be elevated in severe COVID-19 patients compared to mild cases and linked to the interaction between IFN-γ and IL-6/sIL-6R signaling." (PMID 35062368, 2022). "These commonalities may explain why AID patients treated with biologicals such as IL-1 inhibition, TNFα inhibition, and IL-6 inhibition are not at greater risk of severe COVID-19." (PMID 36034552, 2022). "A total of 500 COVID-19 patients with elevated cardiac biomarkers were studied for the analysis of myocardial abnormality through cardiac enzymes, inflammatory biomarkers, and the expression analysis of various cytokines, including IL-1, IL-6, IL-10, IL-17, and IL-25 genes." (PMID 36298704, 2022). "Therefore, the excessive IL-6 concentration in COVID-19 patients may be a reason for the increased number of activated T helper 17 cells seen in these individuals." (PMID 35782361, 2022). "Surprisingly, we could not find any correlation between BChE activity and Interleukin-6 (IL 6), an inflammation marker often associated with the COVID-19-related cytokine storm." (PMID 36140551, 2022). "IL-6 and IL-2R were independent risk factors for severe events in all COVID-19 patients based on univariate analysis though multivariate analysis of IL-6 and IL-2R could not be performed due to some missing data." (PMID 36033814, 2022). "The severity of COVID-19 appears to be related to an exacerbated immune response and events associated with vascular injury Several studies have documented the association between COVID-19 severity and circulating levels of C-reactive protein (CRP), interleukin-6, and D-dimer." (PMID 36163447, 2022). "Interestingly, we previously showed that COVID-19 treated with tocilizumab have increased IL-6 in circulation, which correlates with a numerically higher mortality in tocilizumab recipients, and also aligns with a larger study showing no improvement on the clinical status or lower mortality." (PMID 36341409, 2022). "Moreover, IL-6 level is a good predictor in severe COVID-19 cases." (PMID 36675695, 2022). "In COVID-19, serum IL-6 is considered to be a physiologically relevant biomarker associated with disease progression, and it has been proposed that IL-6 receptor blocking medicine could aid in the therapeutic improvement in individuals with severe and critical COVID-19." (PMID 35365239, 2022). "However, a significantly higher percentage of CD14+CD16+ inflammatory monocytes was observed in the peripheral blood of COVID-19 patients admitted to intensive care units (ICUs), associated with markedly high expression of IL-6 as compared to non-ICU patients." (PMID 35287350, 2022). "Both single-cell immune response (endogenous signaling and signaling response to IFNα/IL-2/IL-4/IL-6 and LPS/CL097; factor 10) and plasma proteome (factor 3) data contributed strongly to the variance observed in our samples and were significantly associated with COVID-19 severity." (PMID 35839768, 2022). "However, considering patients with severe and critical COVID-19, no statistical significance was highlighted for the overall risk of secondary infections due to IL-6 antagonists’ treatments." (PMID 35645219, 2022). "A large cohort study showing an independent association between SARS-CoV-2 infection and QTc prolongation, IL-6 levels and QTc maximum in hospitalized COVID-19 patient were directly correlated, suggesting that IL-6 and QTc prolongation are related, but other factors may be involved." (PMID 36135437, 2022). "Finally, some of the immune modifications may have been influenced by the treatment received in severe COVID-19 such as steroids and anti-IL6." (PMID 35962159, 2022).
COVID-19 (continued). "In a situation with rapid, high, dysregulated IL-6 production, such as severe COVID-19 or a cytokine storm, repeated daily administration of an anti-IL-6/anti-IL-6R agent, or alternating daily doses of anti-IL-6 and anti-IL-6R therapies, could neutralise IL-6 activity." (PMID 35928820, 2022). "Thus, the epigenetic changes associated with IL-6 and ACE2 could be used as biomarkers to predict susceptibility to severe COVID-19 in different groups of people." (PMID 35062298, 2022). "However, in COVID-19 patients, IL-6 seems to be the key mediator in initiating hypercoagulation." (PMID 36010203, 2022). "In addition, deferoxamine decreases the levels of IL-6, the central inflammatory cytokine released during COVID-19, indicating that deferoxamine could be a potential drug treatment for COVID-19-induced liver injury." (PMID 35967872, 2022). "Interestingly, elevated IL-6 levels were also found in patients with acute COVID-19." (PMID 35135496, 2022). "Luo found that quercetin, the active component of licorice, has a strong docking ability with IL-6, suggesting that licorice may primarily reduce IL-6 levels in response to COVID-19 inflammatory outbreaks, which represents a prospective therapeutic strategy for moderate COVID-19." (PMID 36120307, 2022). "Further, the flu vaccine can reduce systemic inflammation by reducing IL-6 production and downregulating toll-like receptor signaling pathways, Caspases protein, and FAS-associated death domain (FADD) that can adjust the response to SARS-CoV-2 infection and also decrease the COVID-19 burden." (PMID 36146492, 2022). "Similarly, the numbers of naïve Tregs, memory Tregs and activated Tregs were significantly decreased with higher IL-6 levels, but when the level of IL-6 was 30-fold higher than normal, Tregs were instead increased compared to COVID-19 patients with normal IL-6 levels." (PMID 36403042, 2022). "Therefore, our primary aim was to investigate the association between found SNPs, IL-6 (rs1800796), IL-10 (rs1800896), TNF-α (rs1800629), and IFITM3 (rs12252) and the presence of post-COVID pain in individuals previously hospitalized by COVID-19." (PMID 36233516, 2022). "Based on these findings, monoclonal antibodies targeting the IL-17 and IL-6 signalling pathways, targeting neutrophil activity, systemic corticosteroids and broad activity immunomodulatory drugs can help dampen the hyper-inflammatory events that are driven by neutrophils in COVID-19 patients." (PMID 35980979, 2022). "It was, however, evidenced that renalase plasma levels measured in COVID-19 patients were significantly decreased compared to that of the control group, and demonstrated a negative correlation with inflammatory cytokines plasma levels, namely, IL-1β, IL-6, and TNF-α." (PMID 36132227, 2022). "In this regard, Gal-1 appears to be involved in the COVID-19 pathogenesis, finding a correlation between its blood level, proinflammatory cytokines, and clinical parameters (chest radiography, dry cough); elevated serum Gal-1 values were correlated with IL-1β, IL6, IL-10, IL-23, and IL-33." (PMID 35897786, 2022). "This suggests that in critical COVID-19, strong elevation of IL-6 (e.g., > 100-120 pg/mL) and CRP levels (e.g., > 160-200 mg/L) could reflect augmented IL-6 cis-signalling in the attempt to exert homeostatic roles, while IL-10 further strengthens the predominance of SOCS3 over STAT3 signal." (PMID 35340805, 2022). "The association between IFN-α, IL-6, and CXCL10 may reflect the systemic immune response against SARS-CoV-2 invasion into pulmonary circulation, which might be an early predictor of respiratory failure due to COVID-19." (PMID 35237279, 2022). "SOCS3 could disrupt this vicious cycle in severe COVID-19 by inhibiting IL-6 signaling." (PMID 35782361, 2022). "Therefore, the role of IL-6 in COVID-19 is irreplaceable by other cytokines." (PMID 36506506, 2022). "Therefore, continuous measurement of IL-6 level is suggested in affected subjects with COVID-19." (PMID 35619180, 2022).
COVID-19 (continued). "Thus, it is reasonable to hypothesize that, albeit high IL-6 and glycemia levels might both simply sense an increased severity of COVID-19, the pro-inflammatory effect of glycemia could eventually hamper the effect of anti-inflammatory biologicals." (PMID 35329890, 2022). "Furthermore, the authors reveal prior significant, unreported correlations between circulating DPP4 activity and CRP, D-dimer, IL-6 and peripheral blood lymphocyte count, which are all essential parameters currently used in the everyday clinical care of COVID-19 patients." (PMID 35195023, 2022). "A burst of pro-inflammatory cytokines such as IL-6, TNF-α, G-CSF, IL-1β, and IL-7 secretion caused by the SARS-CoV-2 invasion and excessive inflammation in the lungs, often referred to as a cytokine storm, is thought to be a major cause of death in patients with COVID-19." (PMID 35273506, 2022). "However, IL-6 was associated with Lymphocytes (r = 0.59, p<0.05); IL-10 was associated with Eosinophils (r = 0.60, p<0.05); and TNF-ɑ was associated with Basophils (r = 0.56, p<0.05), all in COVID-19 unexposed cases." (PMID 36094915, 2022). "Furthermore, we identified significant positive correlations between NEAT1 and CCL2, and IL-6, which may explain its pathological role in COVID-19 by targeting CCL2 and IL-6 and increasing their production, specifically in the severe form of the disease." (PMID 35982898, 2022). "Importantly, patients with severe COVID-19 show conspicuous increases in cytokines, including interleukin (IL)-6, monocyte chemoattractant protein (MCP)-1, IL-8, tumor necrosis factor (TNF)-α, IL-1, IL-18, and IL-17, with characteristics of the cytokine storm (CS)." (PMID 36147356, 2022). "In COVID-19 patients, it has been hypothesized that the high levels of IL-6, IL-8 and IL-10 released by multiple cell types at the site of SARS-CoV-2 infection may alter the number and function of NK cells and neutrophils, thus compromising their mutual equilibrium." (PMID 35844604, 2022). "Furthermore, it was reported that soluble triggering receptor expressed on myeloid cells and an IL-6-based algorithm could serve as a very sensitive marker for early discrimination among patients with adverse reactions among COVID-19 patients." (PMID 35185933, 2022). "In addition, the response to IL-6 in COVID-19 seems to be similar in the presence or absence of pregnancy, indicating that pregnancy does not necessarily aggravate the proinflammatory responses (at least the leucocyte responses) in COVID-19." (PMID 35901034, 2022). "However, further research is required to clarify the role of IL-6 on post-COVID-19 fatigue in women and men (together and separately) and whether this cytokine might be a valuable biomarker of viral virulence." (PMID 35624943, 2022). "We found that plasma exosomes from COVID-19 patients significantly induced the production of the same set of cytokines and chemokines that contribute to the severity of COVID-1949–53, including IL-6, IL-8, TNF-α, IFNγ, CCL1, and GDF-15, in PBMCs compared with those from non-COVID donors." (PMID 36526691, 2022). "On the other hand, the effect of the anti-IL-6 monoclonal antibody tocilizumab on patients hospitalized with COVID-19 is more controversial, although tocilizumab use may be associated with a short-term mortality and a reduction in the need for mechanical ventilation." (PMID 35085321, 2022). "In addition, TGF-β and IL-6 were upregulated in COVID-19 patients, suggesting that targeting these cytokines may improve COVID-19 outcomes." (PMID 35432324, 2022). "Also, IL-6 was found to be elevated in patients with COVID-19 and related to a poor prognosis." (PMID 36012146, 2022). "Therefore, the method to block the signal transduction pathway of interleukin-6 could be a potential treatment for severe COVID-19 patients." (PMID 36705224, 2022).